CXCR4 (C-X-C motif chemokine receptor 4)
Diseases named in the same sentence as CXCR4 in open-access papers (continued):
Sharing a sentence is not in itself a finding about the gene and the disease.
triple-negative breast carcinoma (45 papers, 2011 to 2026). An invasive breast carcinoma which is negative for expression of estrogen receptor (ER), progesterone receptor (PR), and human epidermal growth factor receptor 2 (HER2). "A recent preclinical study has shown that combining immunotherapy with CXCR4 blockade in the context of triple-negative breast cancer leads to enhanced therapeutic efficacy." (PMID 40822347, 2025). "A central theme is redox priming: by elevating ROS, TQ suppresses NF-κB signaling and lowers pro-metastatic CXCR4, thereby limiting migration and invasion in triple-negative breast cancer models." (PMID 41303508, 2025). "MLK3 has been also shown to be involved in the invasion of triple-negative breast cancer (TNBC) cells triggered by C-X-C chemokine receptor type 4 (CXCR4)/stromal cell-derived factor 1 (CXCL12)." (PMID 35409206, 2022). "The use of CXCR4 inhibitor can effectively inhibit the early metastasis of triple negative breast cancer." (PMID 36424557, 2022). "This is surprising considering that we would expect the more aggressive triple negative breast cancer would harbor a more angiogenic and metastatic microenvironment with increased CXCR4 expression." (PMID 35754051, 2022). "TQ was found to inhibit the expression of CXCR4 in MDA-MB-231 triple negative breast cancer (TNBC) cells in a dose- and time-dependent manner." (PMID 30564115, 2018). "In this study, we investigated the effects of CXCR4 gene silencing on cisplatin chemosensitivity in human triple-negative breast cancer cell lines." (PMID 25544759, 2015). "High expression of CXCR4 or CCR5 on tumor was found to be associated with poor prognosis, and CXCR5 on tumor was associated with poor chemotherapy response in the present cohort with locally advanced triple-negative breast cancer." (PMID 39001456, 2024). "Furthermore, LPAR1 heterodimerises with C-X-C chemokine receptor type 4 (CXCR-4) and inhibits CXCL12-induced CXCR4 signalling, while LPA/LPAR1 blocks CXCL12/CXCR4-induced migration of triple-negative breast cancer cells." (PMID 38607068, 2024). "In triple negative breast cancer patients, high cytoplasmic CXCR4 expression was related to lower distant recurrence and better recurrence-free survival, while high CXCL12 expression was associated with larger tumor size, positive lymph node metastasis, and higher pathologic stage." (PMID 35079936, 2022). "Moreover, patients with triple-negative breast cancer with high expression of CXCR4 had a poor prognosis compared to patients with low CXCR4 expression." (PMID 33406809, 2021). "CXCR4 is critically involved in triple-negative breast cancer metastasis." (PMID 32872485, 2020). "Therefore, to study if CXCR4 signaling in the tumor microenvironment supports cancer metastasis initiation, we engrafted the triple negative breast cancer cell line MDA-MB-231-B in the cxcr4bt26035 (odysseus or ody) mutant with deficient cxcr4b36." (PMID 30787324, 2019). "Therefore, we suggest that neutrophilic Cxcr4 signaling plays a crucial role in the early steps of metastases formation of triple negative breast cancer as well as other tumor types." (PMID 30787324, 2019). "Furthermore, high CXCR4 expression was also correlated to poor clinical outcome in triple negative breast cancers, which are difficult to treat." (PMID 21915267, 2011). "In addition, a CXCR4 blockade can improve anti-PD-L1 therapy in triple negative breast cancer." (PMID 34869590, 2021). "Here, we investigated integrated effects of ECM mechanical stiffness and signaling through CXCR4 on activation of Akt and ERK in triple-negative breast cancer (TNBC)." (PMID 40796929, 2025). "Inhibited invasion, migration, and proliferation of triple-negative breast cancer cells by downregulating MMP-9 and CXCR4, implying use in treating invasive breast cancer." (PMID 40297577, 2025). "In triple-negative breast cancer, FOXC1 can increase cell metastasis by stimulating the transcription of CXC chemokine receptor-4 (CXCR4)." (PMID 39093497, 2024).
triple-negative breast carcinoma (continued). "Metastatic triple-negative breast cancer (TNBC) cells, including MDA-MB-231, highly express C-X-C chemokine receptor type 4 (CXCR4) to maintain reactive oxygen species (ROS) and cell migration." (PMID 38655233, 2023). "Sigle knockout of CXCR4 or CXCR7 and co-knockout of CXCR4 and CXCR7 significantly reduced the proliferation, migration, and invasion of triple-negative breast cancer MDA-MB-231cells." (PMID 35079936, 2022). "The CXC chemokine receptor 4 (CXCR4) is overexpressed in many cancers including non-small cell lung cancer (NSCLC) and triple negative breast cancer (TNBC)." (PMID 26848769, 2016). "By concurrently disengaging the CXCR4/CXCL12-mediated immunosuppressive microenvironment and promoting tumour-specific immunity, this dual-action strategy provides a novel and synergistic approach to target drug resistance in triple-negative breast cancer." (PMID 41002447, 2025). "These strategies can also be combined with additional remote loading strategies for silicasomes and liposomes to deliver GSK3 and CXCR4 inhibitors, with additional impacts on the diversity of immune landscapes that appear in PDAC, triple-negative breast cancer, colon, and lung cancer." (PMID 37892935, 2023). "In triple-negative breast cancer cells, OME inhibits invasion in vitro and lung metastasis in vivo through a genomic pathway involving downregulation of the G-protein coupled receptor CXCR4, which is involved in tumor promotion and metastasis." (PMID 32731514, 2020). "In addition to increased CXCR4 expression, a stiff ECM also increases basal activation of Akt and ERK as well as signaling through these kinases in response to CXCL12-α and EGF and promotes migration of triple negative breast cancer (TNBC) cells." (PMID 40796929, 2025). "This study aimed to verify the effects of rP21 interaction with CXCR4 from non-tumoral cells (MCF-10A) and triple-negative breast cancer cells (MDA-MB-231)." (PMID 33195200, 2020).
rheumatoid arthritis (43 papers, 2005 to 2026). A chronic, systemic autoimmune disorder characterized by inflammation in the synovial membranes and articular surfaces. "Focusing on rheumatoid arthritis, which is the focus of our current analysis, the pathogenic role of CXCR4 is particularly prominent." (PMID 41481752, 2026). "The CXCL12/CXCR4 axis has been implicated in the pathogenesis of several types of inflammatory arthritis and autoimmune diseases, including rheumatoid arthritis (RA), osteoarthritis (OA), systemic lupus erythematosus (SLE), and ankylosing spondylitis (AS)." (PMID 36979628, 2023). "For example, GRK6 deficiency is associated with impaired desensitization and enhanced CXCR4-mediated neutrophil migration and has been implicated in the pro-inflammatory response seen in rheumatoid arthritis." (PMID 23497290, 2013). "Thus, the CXCL12/CXCR4 axis is associated with various infectious and inflammatory diseases, including osteoarthritis (OA) and rheumatoid arthritis (RA)." (PMID 41331944, 2025). "As CXCR4 is up-regulated in Classical Monocytes from rheumatoid arthritis patients, they can be expected to migrate towards CXCL12." (PMID 40453083, 2025). "In active rheumatoid arthritis (RA), circulating B-cell phenotyping reveals an enhanced expression of CXCR4 compared with healthy individuals." (PMID 38519141, 2024). "The effect of ITIH4 on CXCR4 was analyzed via knockdown studies in rheumatoid arthritis fibroblast-like synoviocytes (RA-FLS), demonstrating the significant downregulation of CXCR4 protein expression validated by Western blot in RA-FLS." (PMID 39311312, 2024). "The clinical relevance of the CXCR4/CXCL12 axis has been demonstrated in rheumatoid arthritis and multiple sclerosis." (PMID 37736772, 2023). "The involvement of the CXCR4/CXCL12 axis in autoimmune and inflammatory diseases is undisputed as treating rheumatoid arthritis, inflammatory bowel disease or lupus erythematodes with CXCR4-antagonists revealed beneficial outcomes." (PMID 26375818, 2015). "CXCR4 is involved in several diseases such as angiogenesis, metabolic and neurological disorders, rheumatoid arthritis and in different forms of metastatic cancer." (PMID 22693649, 2012). "Early studies showed that the CXCL12/CXCR4 chemokine axis is involved in several inflammatory diseases such as rheumatoid arthritis, acute lung injury, and sepsis." (PMID 22073304, 2011). "The CXCL12/CXCR4 chemokine axis is involved in several inflammatory diseases such as rheumatoid arthritis, acute lung injury, and sepsis." (PMID 22073304, 2011). "In addition, HMGB1 in its reduced form binds to CXCL12 via the chemokine receptor CXCR4 in rheumatoid arthritis (RA), and a high concentration of CXCL12/HMGB1 hybrid complex is dependent on the JAK/STAT pathway to maintain the inflammatory response." (PMID 38156383, 2023). "Also, in rheumatoid arthritis, CXCR4 and CXCL12 have been proposed to be important in the disease precipitation." (PMID 27519689, 2016). "It is of interest that increased numbers of CXCR4+ leukocytes have also been recently detected in other chronic inflammatory diseases, namely in the synovia of joints affected by rheumatoid arthritis and in the colonic tissue of patients with ulcerative colitis patients." (PMID 24695674, 2014). "As CXCR4 is highly expressed by all immune cells, including monocytes and macrophages, we hypothesize that CB could also downmodulate monocyte-driven inflammation in rheumatoid arthritis." (PMID 37822935, 2023). "It has been reported that the SDF-1/CXCR4 axis is constitutively expressed in a wide range of tissues such as the brain, heart, kidney, liver, lung, and spleen and also involved in several diseases such as rheumatoid arthritis, ischemic cardiomyopathy, and several brain diseases." (PMID 26300925, 2015). "The CXCL12/CXCR4 axis also participates in the recruitment of inflammatory cells as shown in animal models of allergic airway disease and rheumatoid arthritis (RA)." (PMID 16507142, 2006).
rheumatoid arthritis (continued). "Currently, active study of the targeting of the CXCL12/CXCR4/CXCR7 axis in the treatment of malignancy, rheumatoid arthritis, and multiple sclerosis is being carried out." (PMID 36077592, 2022). "Considering that SDF-1/CXCR4 signaling is involved in the pathogenesis of rheumatoid arthritis (synovium-derived SDF-1 was increased over 10-fold in RA patients), dioscin may exert multiple protective effects on arthritis." (PMID 31511824, 2019). "Furthermore, our research explored the potential connection between rheumatoid arthritis (RA) and ulcerative colitis (UC) at the miRNA and gene levels, particularly focusing on the two key genes CCR7 and CXCR4." (PMID 41481752, 2026). "Moreover, studies in patients with rheumatoid arthritis (RA) showed that fibroblast-like synoviocytes (FLS) constitutively express CCR2, CCR5, CXCR3,and CXCR4; in addition, stimulation with CCL2, CXCL12, CXCL9, and CXCL10 enhances FLS migration and proliferation." (PMID 28883822, 2017).
chronic lymphocytic leukemia (42 papers, 2008 to 2025). "CXCR4 overexpression and constitutive activation are well-documented features across various mature B-cell malignancies, including chronic lymphocytic leukemia (CLL), mantle cell lymphoma (MCL), and certain subtypes of follicular lymphoma (FL)." (PMID 40076664, 2025). "In a prospective setup, 68Ga-pentixafor PET/MRI was also used in chronic lymphocytic leukemia, as CXCR4 has been advocated to play a crucial role in BM infiltration in this leukemia subtype." (PMID 37290799, 2023). "CXCR4 is of particular interest in chronic lymphocytic leukemia (CLL) and diffuse large B-cell lymphoma (DLBCL), having been associated with adverse prognosis in both diseases." (PMID 34363012, 2021). "CXCR4 hyperactivation resulted in an expansion of transitional B1 lymphocytes, which represent the precursors of chronic lymphocytic leukemia (CLL)." (PMID 34363012, 2021). "The hypoxia-inducible factor 1 (HIF-1) and the CXCL12/CXCR4 axis regulate the interaction of chronic lymphocytic leukemia cells and the tumor microenvironment." (PMID 34207596, 2021). "In patients with chronic lymphatic leukemia HIF-1α correlates with CXCR4 expression and appears to have a relevant role in pathogenesis." (PMID 29865880, 2018). "For instance, a number of studies pointed out an important role of CXCR4 signaling in Chronic Lymphocytic Leukemia (CLL)." (PMID 30619343, 2018). "For example, CXCR4 is overexpressed in ovarian and B-cell chronic lymphocytic leukemia and is also involved in their proliferation, apoptosis and metastasis." (PMID 27409174, 2016). "In view of the crosstalk between phosphoinositide 3-kinases and CXCR4 in chronic lymphocytic leukemia, phosphoinositide 3-kinases inhibitors target CXCR4 signaling and overcome stromal cell-mediated drug resistance." (PMID 22811589, 2012). "Furthermore, the CXCR4 bis(cyclam) ligand BAT1 has been used for the targeted delivery of doxorubicin to CXCR4+ chronic lymphocytic leukemia model, exhibiting a similar dual action mechanism." (PMID 40307933, 2025). "The interaction of cancer cells with the surrounding microenvironment plays a critical role in chronic lymphocytic leukemia (CLL), and MM cells utilize the CXCR4/CXCL12 axis for bone marrow homing." (PMID 35056696, 2022). "In addition, significant linkage has been found for chronic lymphocytic leukemia (CLL), at 2q21.2, which contains the chemokine receptor (CXCR4) gene." (PMID 37379307, 2023). "It has been shown that BCR signaling could directly interact with the microenvironment by decreasing the expression of CXCR4 and CD62L, two major players of nodal and marrow stroma in chronic lymphocytic leukemia." (PMID 29207605, 2017).
renal carcinoma (42 papers, 2008 to 2026). A carcinoma arising from the epithelium of the renal parenchyma or the renal pelvis. "Conversely, other studies have linked CXCR4 to pathways related to cell survival, migration, angiogenesis, renoprotection, and Treg function in renal cancer." (PMID 39192987, 2024). "ADCY7 plays a role in the CXCR4 pathway, and its deficiency has been found in patients with renal cancer-related muscle atrophy." (PMID 34688260, 2021). "As CXCR4 has been associated with the metastasis of renal cancers, CXCR4 expression may be a potential molecular marker for the increased cell invasion and migration abilities, which are induced by tumor-derived exosomes." (PMID 24765179, 2014). "Previous evidence demonstrates that CXCR4 inhibition impairs the function of Tregs in renal cancer and malignant mesothelioma." (PMID 37142825, 2024). "In this manuscript, the efficacy of the new CXCR4 antagonist, R54, was evaluated on peripheral Tregs isolated from 77 primary renal cancer patients." (PMID 38704478, 2024). "A newly developed CXCR4 antagonist, peptide R29, reverts peripheral Tregs’ suppressive capability in primary renal cancer patients." (PMID 37142825, 2024). "CXCR4 overexpression in renal cancer cells increases invasiveness, whereas CXCR4 silencing inhibits RCC cell growth and metastasis." (PMID 34688260, 2021). "The CXCL12–CXCR4 signaling pathway is emerging as a novel potential therapeutic target for renal cancer, CXCR4 being overexpressed in renal malignant cells, contributing to tumour dissemination and metastasis." (PMID 30271792, 2018). "Enhanced CXCR4 expression was detected in several human renal carcinoma samples, while only minimal CXCR4 expression was detected in normal kidney tissues." (PMID 28279221, 2017). "Wang and colleagues reported that silencing of CXCR4 by RNA interference inhibits cell proliferation and metastasis of human renal cancer cells." (PMID 27517626, 2016). "CXCR4 antagonists seem to regulate mTOR signaling in renal cancer cells, offering new therapeutic opportunities and targets to overcome resistance to mTOR inhibitors." (PMID 27891093, 2016). "Several researches also had demonstrated the importance of signaling of CXCR4 in cell-cycle regulation and apoptosis of renal cancer cells." (PMID 26526157, 2015). "For example, neuritin could induce expression of the chemokine receptor CXCR4 in renal cancer, thereby increasing cell viability and the migratory, i.e., metastatic, potential of the tumor cells." (PMID 37092449, 2023). "CXCR4 is expressed in cancer stem cell populations in tumors, as it contributes to developing drug resistance and confers invasive and metastatic properties in renal cancer cells." (PMID 36551144, 2022). "Of note, overexpression of CXCR4 is also associated with poor survival and worse prognosis in ccRCC, and the antagonist of CXCR4 reversed the tumor-promoting microenvironment in renal cancer, indicating that CXCR4 may be a theranostic target for ccRCC." (PMID 34180759, 2021). "Additionally, CXCR4 antagonism (AMD3100) reverts the suppressive activity of activated Tregs (CTLA4+/CXCR4+/PD-1+/ICOS+) in renal cancer or reprograms Tregs in human mesothelioma." (PMID 30364244, 2018). "The SDF-1/CXCR4 pathway has been suggested as a target for renal cancer therapy, and dose-dependent increases in SDF-1 levels have been reported previously in normal nontumour-bearing mice treated with sunitinib in a previous study, which further supports our results." (PMID 19904265, 2009). "Therefore, we evaluated theexpression of CXCR4 in renal cancer cell lines and specimens andcorrelated these results with the patients' clinicopathological parameters andsurvival." (PMID 19266088, 2008). "CXCR4 and CXCL-12 responses to cisplatin were monitored for 21 days in renal cancer organoid modeling in alginate." (PMID 36551144, 2022).
renal carcinoma (continued). "Collectively, we conclude that spheres and CXCR4+MET+CD44+ cells share a gene signature that distinguishes them from controls and characterizes stem cells in renal carcinoma." (PMID 32066735, 2020). "We have also found that MYBBP1A knock down increases the expression of CD34, NANOG and CXCR4, which are target genes of c-MYB, exclusively in renal carcinoma cell lines that express high levels of c-MYB." (PMID 30781655, 2019). "As this review was going to press, de-repression of CXCR4, which has a CGI promoter, was shown to facilitate metastasis in a renal cancer cell line." (PMID 23341493, 2013). "Thus, regulation of the CXCL12, CXCR4, and CXCR7 genes appears to be of minor importance for epithelialization in forming nephrons but might be relevant in diseases including renal carcinoma and fibrosis that are associated with epithelial-to-mesenchymal transition." (PMID 22880115, 2012). "Hypoxia-induced lncHILAR promotes renal cancer metastasis via ceRNA in the miR-613/206/1-1-3p/jagged-1/Notch/CXCR4 signaling pathway." (PMID 38169586, 2024). "These three CXCR4 inhibitory peptides were proven to be effective in inhibiting CXCR4-dependent migration and binding, P-ERK1/2-induction, calcium efflux, and tumor growth of renal cancer cells." (PMID 27891093, 2016). "SN12C and A498 cells migrated toward CXCL12 and CXCL11; the migration toward CXCL12 was inhibited by anti-CXCR4 and Peptide R, whereas CXCL11-induced migration was inhibited by anti-CXCR7 demonstrating that both chemokine receptors affected migration in renal cancer cells." (PMID 24991762, 2014). "Small molecule CXCR4, CXCR4 and SDF-1 antagonists could be attractive therapeutic candidates in future clinical trials for renal cancer." (PMID 23039915, 2012). "In renalcell carcinoma, the respective expression rate for CXCR4 was 100%(113/113) and varied from weak (34%), intermediate (42%), to strong (24%).Negative controls of human renal cancer remained negative for all tissuesamples (N = 113, not shown)." (PMID 19266088, 2008). "Ontology revealed that enhancer CpGs from the normal group are weakly associated with pathways commonly linked tumorigenesis (e.g., EMT and renal carcinoma signaling), unlike the tumor enhancer CpGs that were enriched for cancer-associated pathways like MAPK, PTEN, and CXCR4 signaling." (PMID 37120552, 2023).